CXCL8 (C-X-C motif chemokine ligand 8)
Diseases named in the same sentence as CXCL8 in open-access papers (continued):
Sharing a sentence is not in itself a finding about the gene and the disease.
head and neck squamous cell carcinoma (31 papers, 2012 to 2025). A squamous cell carcinoma that arises from any of the following anatomic sites: lip and oral cavity, nasal cavity, paranasal sinuses, pharynx, larynx, and salivary glands. "systematically analyzed head and neck squamous cell carcinoma (HNSCC) datasets, revealing consistently elevated CXCL8 expression in tumor samples." (PMID 41445742, 2025). "IL-8 (CXCL-8) is a member of the CXC chemokines family and IL-8 receptors CXCR1 and CXCR2 are expressed on various normal and cancerous cells including head and neck squamous cell carcinoma." (PMID 22507529, 2012). "Indeed, we have shown that endothelial cell-derived CXCL8 and EGF have significant effects on the survival and motility of head and neck squamous cell carcinoma cells." (PMID 26287605, 2015). "However, in HNC, especially in head and neck squamous cell carcinoma, the chemokine CXCL8/9/10/11/13 has not been clearly explored for its diagnosis and prognosis." (PMID 35905218, 2022).
nasopharyngeal carcinoma (30 papers, 2009 to 2026). A carcinoma arising from the nasopharyngeal epithelium. "To explore the effect of CXCL8-CXCR2 signaling in nasopharyngeal carcinoma, we performed immunohistochemistry staining for CXCR2 and CXCL8 in an NPC tissue microarray and found CXCR2 localized in both tumor cells and stromal cells; CXCL8 was frequently observed in the cytosol of tumor cells." (PMID 34124076, 2021). "However, how the activity of CXCR2 and its ligand CXCL8 affects the development of nasopharyngeal carcinoma (NPC) remains unknown." (PMID 34124076, 2021).
respiratory failure (30 papers, 2012 to 2026). The significant impairment of gas exchange within the lungs resulting in hypoxia, hypercarbia, or both, to the extent that organ tissue perfusion is severely compromised. "Further, multivariate analyses showed that IL-8/CXCL8 concentration was an independent predictor for development of respiratory failure (adjusted OR 1.12 per unit rise, 95%CI 1.02–1.23) adjusted for confounders such as old age and underlying comorbidities." (PMID 27434276, 2016). "High plasma IL-8/CXCL8 [median(IQR), 17.6(5.9–27.3) vs 4.3(3.6–9.0) pg/mL, P<0.001) and IL-6 [16.2(7.4–37.7) vs 8.7(5.5–15.0) pg/mL, P = 0.026] concentrations were significantly associated with development of respiratory failure; the same cytokines were also associated with ICU admission/death." (PMID 27434276, 2016). "Plasma IL-8/CXCL8 (adjusted OR 1.12, 95%CI 1.02–1.23 per unit increase, P = 0.021) and HMGB1 (adjusted OR 1.42 per unit increase, 95%CI 1.08–1.87, P = 0.012) concentrations were independent predictors for respiratory failure, as well as for ICU admission/death." (PMID 27434276, 2016).
Nephropathy (29 papers, 2006 to 2025). A nonspecific term referring to disease or damage of the kidneys. "CXCL-8 exerts a chemoattractant effect for neutrophils and is related to proteinuria associated with kidney disease, and its urinary increase has been reported in acute phases of glomerulonephritis and nephropathies." (PMID 36117588, 2022). "Interleukin, the multifunctional inflammatory cytokines are closely associated with various renal diseases and the injury of kidney residential cells, such as IL-6, CXCL8, IL-1β, IL-2 and IL-4." (PMID 32765640, 2020). "For instance, CCL2/MCP-1 and CXCL8/IL-8 are the chemokines more commonly associated with pediatric renal diseases." (PMID 24692841, 2014). "The molecules CXCL-8 and CCL-2 have been described as participating molecules in kidney disorders of different orders, such as lupus nephritis, where the urinary excretion of CXCL8 is related to renal inflammatory activity." (PMID 36117588, 2022). "In addition, CXCL8 is correlated with kidney disease in MM patients, though the mechanisms behind this remain unclear." (PMID 40940985, 2025). "While CXCL8 serum levels vary in MM patients, high levels are positively correlated with disease activity markers like B2M, LDH, anemia, and kidney disease." (PMID 40940985, 2025).
bronchiolitis (28 papers, 2006 to 2025). Inflammation of the bronchioles characterized by swelling of the bronchioles and mucus accumulation. "Moreover, CXCL8 plays a role in the pathogenesis of the lower respiratory tract infection bronchiolitis, a common respiratory tract disease caused by the respiratory syncytial virus (RSV)." (PMID 36553678, 2022). "Indeed, elevated levels of IL-6, IL-8 (CXCL8), CCL2, and CCL4 have been reported in cerebrospinal fluid from patients with severe bronchiolitis and hRSV-associated encephalopathy." (PMID 30936869, 2019).
Autoimmunity (27 papers, 2009 to 2025). The occurrence of an immune reaction against the organism's own cells or tissues. "CXCL8-dependent neutrophil chemotaxis to the pancreas precedes autoimmunity, and CXCR1/2 blockade mitigates insulitis and T1D development in preclinical models." (PMID 40718478, 2025). "In this model, which was re-iteratively perfected into a paradigm of autoimmunity, a certain inflammatory trigger initiates the production of cytokines and chemokines (such as IL-8/CXCL8) that attract myeloid cells to the site of inflammation." (PMID 32604901, 2020). "Moreover, the pleiotropic functions of CXCL8 in different tissues and cell types—beyond neutrophil chemotaxis—are incompletely characterized in the context of human autoimmunity." (PMID 40718478, 2025). "IL-17 plays a key role in chronic inflammatory disorders and autoimmunity, and this cytokine stimulates chemokines (e.g., CXCL1, CXCL2 and CXCL8) and granulopoiesis." (PMID 35641947, 2022).
dementia (27 papers, 2006 to 2025). Loss of intellectual abilities interfering with an individual's social and occupational functions. "Macrophages are the principal target cell and mediator of neuronal injury in modifying the production of astrocyte CXCL8 in HIV-associated dementia." (PMID 34483726, 2021). "The results show that CSF chemokine concentration of MCP-1/CCL2, MIP-1α/CCL3, MIP-1β/CCL4, RANTES/CCL5, IL-8/CXCL8 and fractalkine/CX3CL1 is positively correlated with the severity of dementia and the viral load, indicating HIV induced brain damage." (PMID 16712719, 2006).
diabetic retinopathy (27 papers, 2009 to 2025). "In parallel, the intraocular cytokine milieu in diabetic retinopathy consistently shows elevated levels of IL−6, IL−8 (CXCL8), and CCL2 (MCP−1)." (PMID 41394857, 2025). "CXCL8 is involved in the development of multiple complications, such as diabetic retinopathy, cardiovascular disease (CVD), and infection." (PMID 34790229, 2021). "While virtually nothing is known regarding CXCL2 and CXCL3 in diabetic retinopathy, CXCL8 (also called IL-8) has consistently been found to be elevated in the vitreous of diabetic retinopathy patients." (PMID 29626212, 2018). "Concentrations of CCL8, CCL2, CXCL8 and CXCL10 may be associated with diabetic eye disease, especially in diabetic retinopathy and diabetic macular edema." (PMID 38790059, 2024). "CCL2 and CXCL8 were elevated in eyes with diabetic retinopathy (but not in the diabetic patients without retinography group) compared to non-diabetic controls, in keeping with reports from previous studies." (PMID 22511846, 2012).
migraine (27 papers, 2019 to 2025). "A study of migraine patients revealed that CCL3 and CXCL8 were both found to be increased interictally in blood serum from patients with migraine in contrast to healthy control individuals." (PMID 35295531, 2021). "Additionally, blood analysis from migraine patients showed higher CXCL8 levels in samples collected 2 and 4 h post-attack onset (headache), in contrast to healthy controls." (PMID 35295531, 2021).
endotoxemia (26 papers, 2006 to 2024). "However, it is worth mentioning that CCL11/eotaxin-1, besides its role in attracting eosinophils, can exert a specific regulatory function of neutrophil recruitment in vivo as has been shown in a mouse model of endotoxemia via probable down-regulation of CXC chemokine CXCL8/IL-8." (PMID 22529962, 2012).
esophageal cancer (26 papers, 2010 to 2026). A primary or metastatic malignant neoplasm involving the esophagus. "Using the TCGA database, we confirmed that both CXCR2 and CXCL8 are overexpressed in ESCC, whereas CXCL8 exhibited a high diagnostic value for esophageal cancer (AUC: 0.95, 95% CI: 0.893–1.000)." (PMID 40722739, 2025). "Further analysis using the K–M survival curve revealed that elevated levels of CXCL8 in esophageal carcinoma were linked to unfavorable outcomes." (PMID 40722739, 2025). "Increased CXCL-8 expression has been found in endothelial cells, infiltrating neutrophils, tumor-associated macrophages and cancer cells, including oesophageal cancer cells." (PMID 30820705, 2019). "To address this paradox, we interrogated multiple esophageal cancer models, finding myeloid-attracting chemokines-with CXCL8 as a prominent hit-as conserved CIN-driven targets in EAC." (PMID 41811963, 2026). "Immunohistochemical analysis has shown that elevated expression of CXCL-8 and its receptor CXCR-2 is closely associated with invasion depth, pathological stage, and venous invasion in esophageal cancer." (PMID 37359527, 2023). "CXCL-8 is produced by malignant cells, and therefore it can stimulate the growth and progression of various neoplasms, including oesophageal cancer (OC)." (PMID 30820705, 2019). "This signalling cascade was also shown to be involved in CXCL1 signalling in esophageal cancer and in CXCL8 secretion in primary human hepatocytes." (PMID 21044331, 2010). "Additionally, increased expression of CXCL8 has been observed in esophageal cancer." (PMID 37359527, 2023). "Our previous investigations indicated the significant differences between serum levels of CXCL8 and/or CXCR2 in cancer patients and healthy individuals; however, these studies were performed on pancreatic, colorectal as well as esophageal cancer patients." (PMID 34680333, 2021). "Similar correlations were observed in esophageal carcinoma, with CXCL1, CXCL2, CXCL3, and PPBP negatively correlated with EMT, CXCL5 and CXCL6 positively correlated with EMT, and CXCL8 not correlated with EMT." (PMID 37686093, 2023).
steatosis (26 papers, 2015 to 2025). Increased lipid within the cytoplasm of cells. "Alike, CXCL8 was significantly increased in NASH patients as compared to bland steatosis or healthy controls thus demonstrating clinical relevance of the current findings with hepatocyte cultures." (PMID 30547786, 2018). "This approach revealed a spectrum of steatosis, with normal livers containing some steatotic cells and steatotic livers containing some normal cells, and enabled us to identify CXCL8 as a highly specific and conserved marker of steatotic hepatocytes across normal and steatotic livers." (PMID 39881029, 2025). "Additionally, the results of AH patients, NIAAA, and ALD mouse models have indicated that excessive alcohol consumption inhibits the ADRB2/SIRT1/PGC-1α/PPARα pathway, leading to elevated levels of oxidative stress and cytokines such as CCL2, CXCL8, and CXCL10, accompanied by hepatic steatosis." (PMID 39640486, 2024).
Thrombocytopenia (26 papers, 2008 to 2025). A reduction in the number of circulating thrombocytes. "In PMF patients, CXCL8 is associated with leukocytosis, and CXCL10 levels correlate with thrombocytopenia." (PMID 34084749, 2021). "Increased levels of CXCL8 in MDS-patients were also detected in another study investigating serum levels in MDS patients with thrombocytopenia, and similar to AML, the CXCL8-levels then decreased to normal values during cytoreductive treatment and achievement of complete remissions." (PMID 23430540, 2013).
AIDS (25 papers, 2009 to 2025). A syndrome resulting from the acquired deficiency of cellular immunity caused by the human immunodeficiency virus (HIV). "According to our results, most HIV-patients had low CXCL8 and CCL2 levels, a finding probably related to their HIV/AIDS status." (PMID 34829225, 2021).
allergic rhinitis (25 papers, 2008 to 2025). Inflammation of the nasal mucous membranes caused by an IgE-mediated response to external allergens. "The targets of 48 putative therapeutic components in the treatment of allergic rhinitis include IL6, TNF, CXCL8, ICAM1, ILA, MMP9, IL10, and IL1B." (PMID 31611923, 2019).
astrocytoma (25 papers, 2012 to 2025). "CXCL8 expression in the early stage of astrocytoma development is initiated by pro-inflammatory stimuli but later in tumor progression it increases due to reduced microenvironmental oxygen pressure." (PMID 32456359, 2020). "Expression of CXCL8 mRNA and protein were detected in grades II, III, and IV astrocytomas and anaplastic oligodendroglioma." (PMID 32456359, 2020). "Importantly, mRNA for chemokine receptors binding CXCL8, both atypical ACKR1 and conventional CXCR1 and CXCR2, were found in all astrocytoma grades tested by reverse transcription/PCR analysis." (PMID 32456359, 2020).
bacterial meningitis (25 papers, 2007 to 2025). Inflammation of the membranes surrounding the brain and spinal cord due to a bacterial infection. "Increased levels of CXCL8 in the CSF have been correlated with PMN influx in many forms of bacterial meningitis." (PMID 30777092, 2019). "Since high levels of CXCL8 are observed in both bacterial and viral meningitis, but only bacterial meningitis is accompanied by a potent influx of neutrophils, we propose that this additional signal is missing in HSV CNS inflammations." (PMID 28693588, 2017). "IL-8 (CXCL-8 was found to be chemotactic for neutrophils in the CSF of patients with bacterial meningitis." (PMID 23997430, 2013). "In a study on bacterial meningitis, patients carrying the D148E polymorphism had reduced levels of IL-6, IL-1Ra, IL-8/CXCL8, and MCP-1/CCL2 compared with patients not harboring the polymorphism." (PMID 35296074, 2022). "Elevated CXCL5, CXCL8, and CXCL1 and TNFα CSF concentrations have been reported in children with bacterial meningitis." (PMID 31727097, 2019).
metastatic melanoma (25 papers, 2004 to 2024). A melanoma that has spread from its primary site to another anatomic site. "We also found that the circulating levels of MPO, MMP-9, GM-CSF and CXCL8/IL-8 were higher in metastatic melanoma patients than in healthy controls." (PMID 37525065, 2023). "The same study has shown that the frequency of circulating NK cells expressing the receptors for IL-8/CXCL8 is increased in metastatic melanoma patients compared with healthy subjects, agreeing with our results." (PMID 30761123, 2019). "The results of independence testing analysis showed that genes of CXCL8 and THBS1 had a significant increase of gene expression in metastatic melanoma, but a significant downregulation of KIT expression." (PMID 32894090, 2020). "Furthermore, serum concentrations of neutrophil-related factors (MPO, MMP-9, CXCL8/IL-8 and GM-CSF) and NET biomarkers (nucleosomes and CitH3) were higher in stage IV metastatic melanoma patients than in healthy controls." (PMID 37525065, 2023). "In line with previous reports, the serum levels of IL-6 and CXCL8 were not significantly elevated among AP and RP patients, as opposed to higher levels observed in metastatic melanoma patients, similar to previously reports." (PMID 26909604, 2016).
nasal polyps (25 papers, 2008 to 2025). "CXCL8 (IL-8), which attracts neutrophils and eosinophils into the nasal mucosa, provided these have been previously activated by IL-5, plays a further role in nasal polyp inflammation." (PMID 29564208, 2018).
sarcoidosis (25 papers, 2009 to 2025). Sarcoidosis is a multisystemic disorder of unknown cause characterized by the formation of immune granulomas in involved organs. "The BAL exosomes from sarcoidosis patients induced higher levels of IFNγ and interleukin-13 production by PBMCs and CXCL-8 production by epithelial cells in comparison to that induced by exosomes from healthy individuals." (PMID 27738390, 2016). "BAL exosomes from sarcoidosis patients induce the production of inflammatory cytokines by PBMCs and promote the release of CXCL-8 by airway epithelial cells through delivery of pathogen-associated proinflammatory mediators." (PMID 27738390, 2016). "In sarcoidosis, exosomes cause the initiation and progression of inflammatory responses by enhancing the induction of IL-13, INF-gamma, and CXCL-8 production in the lung microenvironment." (PMID 27738390, 2016). "Consistently, monocytes in sarcoidosis patients and, to a lesser extent in active TU, exhibited significantly increased enrichment of genes related to the ‘Inflammatory Response’, including IL1B, CXCL8 and TNF." (PMID 40469525, 2025). "While MET is a hallmark of tissue granuloma formation, blood monocytes in both active TU and sarcoidosis exhibited epithelial–mesenchymal transition (EMT) signatures, including significantly increased expression of GADD45B, CD44, CXCL8, ANPEP and THBS1,30, 31, 32, 33 compared with healthy donors." (PMID 40469525, 2025). "However, the relative frequencies of CXCL8, IL1B, and M4SA1 transcripts were higher in TB samples whereas RORC mRNA was increased in the sarcoidosis samples." (PMID 38385142, 2023).
acute myeloid leukemia (24 papers, 2015 to 2025). Acute myeloid leukemia (AML) is a group of neoplasms arising from precursor cells committed to the myeloid cell-line differentiation. "A significant secretion of CCL3, CCL2, CCL4, CXCL1, and CXCL8 exists in acute myeloid leukemia (AML) cells." (PMID 40148973, 2025). "The contribution of CXCL8 to tumorigenesis has been described in patients with acute myeloid leukemia, in which high CXCL8 levels are secreted by BM mesenchymal stromal cells and support the proliferation and survival of leukemic cells." (PMID 34084749, 2021). "Moreover, BM-MSC-derived CXCL8 supported survival and proliferation of acute myeloid leukemia cells through the PI3K/AKT pathway." (PMID 31885609, 2019). "CXCL8 is the recurrence marker of acute myeloid leukemia (AML)." (PMID 36295640, 2022). "Interestingly and on the same hand, the CXCL8 supporting the survival and proliferation of acute myeloid leukemia (AML) cells via the phosphatidylinositol 3-kinase (PI3K)/protein kinase B (AKT) signaling pathway in the affected BM microenvironment would be mainly secreted by MSCs28." (PMID 33299638, 2020).
acute pancreatitis (24 papers, 2009 to 2025). An acute inflammatory process that leads to necrosis of the pancreatic parenchyma. "Serum CXCL8/IL-8 levels predict AKI in patients with acute pancreatitis, after cardiac surgery and liver transplantation." (PMID 33043785, 2020).
Airway obstruction (24 papers, 2005 to 2024). Obstruction of conducting airways of the lung. "To further investigate if the differences in fMLF induced CXCL8 and MMP-9 in controlled and uncontrolled asthmatics were related to airway obstruction, we performed correlation analysis." (PMID 26663987, 2015).
allergic asthma (24 papers, 2009 to 2025). A asthma with a basis in a pathological type I hypersensitivity reaction. "On the other hand, non-eosinophilic/non-allergic asthma involves increased neutrophilia due to the increased activity of the chemoattractant CXCL8/IL-8 and is associated with corticosteroid resistance and increased disease severity." (PMID 36911735, 2023). "Generally, cytokines play a central role in the pathogenesis of allergic inflammation, with related studies documenting that both pro-inflammatory cytokines and chemokines, including TNF-α, IL-6, NO, and CXCL8, contribute to the pathogenesis and exacerbation of allergic asthma." (PMID 33261109, 2020).